ARID1A (AT-rich interaction domain 1A)
Diseases named in the same sentence as ARID1A in open-access papers (continued):
Sharing a sentence is not in itself a finding about the gene and the disease.
tumor (continued). "Therefore, in this study, we believe that in ARID1A-deficient tumor cells, nPD-L1 is signaled to activate RASGEF1A and the Ras signaling pathway, ultimately leading to resistance to Osimertinib." (PMID 39773749, 2025). "In sharp contrast, around only 0.3% of the PTEN, SMAD4 or ARID1A mutations in tumours (mean: 0.25–0.39) can be described as passengers in this way, suggesting they are true cancer driver genes positively enriched in CRC beyond their level of selection in normal tissue." (PMID 39920335, 2025). "Additionally, low expression of the ARID1A gene is linked to tumor invasion and reduced immune infiltration in OCCC." (PMID 40656893, 2025). "Reduced ARID1A expression may therefore be beneficial for the tumor while its loss has an inhibitory effect." (PMID 40170512, 2025). "Meanwhile, ARID1A deletions or mutations are attributed to the defective chromatin, leading to an abnormal DNA repair mechanism and silencing of this gene, which usually has a tumor suppressive role." (PMID 41369383, 2025). "Understanding the molecular mechanisms underlying tumor suppression or oncogenesis by ARID1A could facilitate the discovery of vulnerabilities to be harnessed therapeutically." (PMID 41049615, 2025). "To further advance our understanding of why ARID1A mutations arise in both early and late tumor development, we generated and evaluated three stable bladder (cancer) cell line models and additionally one transient model, i.e., two normal‐like (UROtsa, HBLAK) and two malignant (T24, JMSU‐1) models." (PMID 40170512, 2025). "However, in advanced tumors, loss of ARID1A due to mutations or its downregulation can lead to a shift in SWI/SNF complex function from tumor‐suppressive to oncogenic." (PMID 40671262, 2025). "Interestingly, even monoallelic inactivation can result in complete loss of ARID1A expression, underscoring its vulnerability as a tumor suppressor gene." (PMID 41020848, 2025). "Thus, ARID1A-loss tumor cells must rely on the glutamate-cysteine ligase synthetase catalytic subunit (GCLC), a rate-limiting enzyme for GSH synthesis, to produce cysteine necessary for GSH production." (PMID 38347608, 2024). "One study reported that a loss of ARID1A was associated with a poorer prognosis and that ARID1A may exhibit a tumour suppressive role." (PMID 38536546, 2024). "Overall, our results support a context-dependent functional link between SWI/SNF and NRF2 mutations across human cancers and implicate ARID1A inactivation in HPV-negative HNSC in promoting tumor progression and survival through activation of the KEAP1-NRF2 signaling pathway." (PMID 38358974, 2024). "In addition, an in vitro trial found higher tumor-infiltrating lymphocytes and PD-L1 expression in the ARID1A-deficient OC cell line." (PMID 38347608, 2024). "Our results have shown that ARID1A deficiency promoted tumor proliferation and metastasis." (PMID 38166741, 2024). "Overall, ARID1A deficiency was associated with increased immune activity in tumour tissues." (PMID 38166741, 2024). "Patients with the ARID1A mutation often have irregular tumor shapes (p<0.05)." (PMID 38904052, 2024). "ARID1A mutations affect several pathways critical for tumor growth." (PMID 38893181, 2024). "Co-mutation of PIK3CA and ARID1A enhances sustained IL-6 production, driving rapid tumor growth." (PMID 39445058, 2024). "However, the exact mechanisms of how Arid1a loss contributes to tumorigenesis vary across tumor types." (PMID 39123453, 2024).
tumor (continued). "In another facet of the tumor milieu, ARID1A's loss appears to recalibrate the immune landscape, evidenced by an influx of tumor‐infiltrating lymphocytes (TILs), notably CD8+ T cells, rendering the immune environment of such tumors more amenable to immunotherapy." (PMID 38374872, 2024). "Increasing evidence has shown that ARID1A deficiency might play a critical role in sculpting tumor environments in various tumors and might be used as pan-cancer biomarkers for immunotherapy outcomes." (PMID 38166741, 2024). "In a study of 55 OCCC, the ARID1A paralogue ARID1B was reported to be mutated in 18% of tumours." (PMID 39272926, 2024). "Furthermore, the present study revealed that HBV-HCC with ARID1A deficiency had a higher level of immune cell infiltration in tumour tissues, which is characteristic of the so-called “hot tumour” and is more prone to ICBs." (PMID 38166741, 2024). "As ARID1A functions in cell cycle inhibition, based on the observed loss-of-function mutation spectrum in various cancers, it is speculated to be a tumor suppressor." (PMID 38365747, 2024). "However, the specific oncogenic mechanism of ARID1A is still unclear, and the variability of ARID1A mutations in different tumors and the impact of ARID1A mutations on tumor prognosis need to be investigated in depth." (PMID 39697230, 2024). "The expression of CXCL13 in baseline tumor tissues, along with an ARID1A mutation in tumor cells, has been identified as a predictor of successful clinical responses in metastatic urothelial carcinoma patients treated with nivolumab, an immune checkpoint therapy, through whole-exome sequencing." (PMID 39409924, 2024). "Importantly though, biomarker research, including mutation analyses of the ARID1A gene, early detection of activated oncogenes, and the silencing of tumor suppressors are strongly advised." (PMID 38029403, 2023). "Further studies will confirm whether the high prevalence of ARID1A variants in tumor samples is valid for other Latin American populations and whether there is a functional relationship between ARID1A and the DNA Interstrand Crosslink Repair genes." (PMID 37182128, 2023). "This tumor type is characterized by an ARID1A mutation frequency of 12-16%." (PMID 36890819, 2023). "Furthermore, analysis of immune-signature revealed that tumour environments of ARID1A-deficient tumours were infiltrated with specific subtypes of immune cells, such as subsets of CD4+, CD8+ T cells and NK cells, type 17 T-helper cells (Th17), and so on." (PMID 37568604, 2023). "However, a recent report shows that ARID1A mutation can enhance the immunogenicity of tumor cells in BC48 and were found to be associated with immune activity in gastrointestinal and microsatellite-stable colorectal cancers." (PMID 38017109, 2023). "ARID1A deficiency may also promote HCC development by altering the tumour microenvironment and vascularity." (PMID 38275587, 2023). "However, how ARID1A mutations alter downstream signaling to promote tumor development is yet to be established." (PMID 38071325, 2023). "Importantly, ARID1A inactivation is associated with poor outcomes and reduced chemosensitivity in many tumor types, including clear-cell OCs." (PMID 37109525, 2023). "ARID1A deficiency would compromise the mismatch repair pathway and increase the number of tumor-infiltrating lymphocytes, tumor mutation burden, and expression of PD-L1 in a subset of malignancies, suggesting that ICB treatment would be more effective in these cases." (PMID 37313463, 2023). "Another cause for the loss of ARID1A can be an ARID1A promoter hypermethylation and it is likely that both mechanisms may work in combination for a tumor to achieve a complete loss of ARID1A proteins." (PMID 37627124, 2023).
tumor (continued). "In summary, ARID1A serves as the essential tumor suppressor in EGFR-mutant LUAD, while loss of ARID1A expression leads to the extensive activation of oncogenic pathways and enables tumor cells to acquire a more aggressive phenotype, finally resulting in the progression of the disease." (PMID 36869329, 2023). "Moreover, in mice with liver-specific Arid1a manipulation, loss of Arid1a presents resistance to tumor initiation whereas ARID1A overexpression accelerates initiation." (PMID 36980292, 2023). "Therefore, the treatment of EZH2‐dependent tumours after ARID1A mutation requires the inhibition of its interaction with proteins in addition to the inhibition of the methylesterase activity of EZH2." (PMID 36883311, 2023). "Mutations in ARID1A in EC have been associated with promoting tumor invasion and metastasis, which may shed light on the significant mortality among women diagnosed with USCs." (PMID 37228503, 2023). "In addition, both tumor cohorts with poor and good responses to neoadjuvant treatment presented mutations in ARID1A, CREBBP, BRCA2 and RAD50, although with significantly different frequencies." (PMID 37373240, 2023). "Gastrointestinal cancers with ARID1A mutations tend to exhibit elevated signatures of anti‐tumour immune cells, including CD8+ T cells, natural killer cells, activated Th1, activated dendritic cells and MHC class molecules, all of which have tumour‐suppressive effects." (PMID 38041544, 2023). "However, only one of these small variants was predicted to drive tumor development; a heterozygous ARID1A variant." (PMID 36968225, 2023). "Finally, we found that, compared with HER2‐positive patients, HER2‐negative patients tended to have a higher tumor mutation burden, particularly in patients with ARID1A mutation." (PMID 37325934, 2023). "This may explain the seeming paradox that ARID1A-deficient tumours tended to show fewer gross chromosomal aberrations compared to ARID1A-proficient tumours." (PMID 38275587, 2023). "Partial or complete loss of ARID1A in GC correlated significantly with tumor type according to Laurén, Epstein–Barr virus status, microsatellite instability, PD‐L1 status, and nodal spread, supporting the notion that the SWI/SNF complex contributes to GC biology." (PMID 36916408, 2023). "Here, we study the impact of ARID1A deficiency on the anti-tumor immune response in EAC." (PMID 38001638, 2023). "Moreover, an ARID1A-deficient mice treatment with anti-PD-L1 antibodies reduced tumor burden and prolonged survival." (PMID 37189643, 2023). "However, analysis of GC data from The Cancer Genome Atlas (TCGA) revealed that loss of ARID1A expression correlates with increased levels of the tumour‐infiltrating lymphocyte (TIL) transcriptome signature." (PMID 38041544, 2023). "Most mutations in Arid1a are frameshift or non-sense mutations that result in the loss of protein, manifested by negative immunohistochemical staining, in keeping with its function as a tumour suppressor." (PMID 38275587, 2023). "Several recent studies reported that ARID1A genetic alterations are linked to tumor development." (PMID 36890819, 2023). "In addition to survival rate, other clinicopathological factors such as lymph node metastasis and tumor infiltration have been positively correlated with loss of ARID1A expression." (PMID 36890819, 2023). "This may be supported by our observation that ARID1A was a subclonal mutation in our multiple-site mutation analysis and thus occurring later during tumor evolution." (PMID 35379887, 2022). "Suggesting that ARID1A mutation were predominantly in CCA with high tumor stage and may involve in CCA progression." (PMID 35070505, 2022). "However, no (L)PVs were detected in the other two most frequently mutated genes, KRAS and ARID1A, in either tumor." (PMID 36291559, 2022).
tumor (continued). "It made us hypothesize that elevated ARID1A mutations in the high-risk team might promote tumor progression and bring about poor prognosis." (PMID 35992824, 2022). "ARID1A deficiency due to somatic mutations have been associated with impaired DNA damage repair in BC, thus prompting the development of synthetic lethality-based therapeutic strategies for ARID1A-mutated neoplasms." (PMID 36686738, 2022). "The use of HDAC6 inhibitors could represent a therapeutic strategy for patients diagnosed with advanced stages of ARID1A‐mutated tumours." (PMID 35167193, 2022). "An illustrative example is offered by ARID1A, a chromatin-remodeling gene that is commonly mutated in cancer, and hypothesized to be tumor suppressive." (PMID 35625590, 2022). "Similarly, ARID1A mutation was demonstrated to protect cancer cells from changes in tumor microenvironment by upregulating ERS." (PMID 35992824, 2022). "In particular, PD-L1 expression was significantly increased in ARID1A-mutated cancers, which could lead to impaired tumor immunity, and this might represent a potential mechanism by which ARID1A-deficient tumors escape immune surveillance." (PMID 35198440, 2022). "Thus, targeting those complementary pathways holds promise in developing new cancer therapies in ARID1A deficient neoplasms." (PMID 36123603, 2022). "Furthermore, tumours harbouring biallelic ARID1A mutations showed high levels of PD-L1 expression and high densities of T cell subpopulations." (PMID 36613564, 2022). "Another study showed how the identification of CTNNB1 alterations, along with ARID1A mutations, could represent an effective way to characterize the tumor aggressiveness of the heterogenous NSMP group." (PMID 35205661, 2022). "Indeed, ARID1A is highly expressed in primary tumors, while, after initiation, loss of ARID1A in metastatic lesions accelerates tumor progression." (PMID 35625590, 2022). "Moreover, ARID1A loss leads to DNA decatenation defects in tumor cells, which is thought to be due to improper localization of TOP2A." (PMID 36123603, 2022). "Furthermore, ARID1A normally suppresses certain HDACs and tumor cells with ARID1A mutations lose this feedback, become HDAC dependent and hence highly sensitive to HDACi." (PMID 34257602, 2021). "In addition, they also found that ARID1A was associated with tumor nodules, vein invasion, and tumor recurrence status in CCA." (PMID 34249744, 2021). "Several relevant genes have been associated with a high tumour mutational burden (including ARID1A, RNF43, BRAF and KM2B in microsatellite instability (MSI) cancers) and may help select MSS tumours for immunotherapy." (PMID 34694371, 2021). "Collectively, ARID1A loss reportedly promotes mutagenicity of the tumor and may induce a similar phenotype to that of POLE-mutated or MMR-deficient tumors, that may play a key role in endometrial carcinogenesis." (PMID 34257552, 2021). "A somatic variant in ARID1A gene (p.R1276∗) was detected in the tumor tissue and ccfDNAs." (PMID 34178989, 2021). "The findings indicate that loss of ARID1a, that is frequent in tumor, may increase mechanotransduction." (PMID 34782888, 2021).
tumor (continued). "In terms of mechanism, loss of ARID1A could affect the efficacy of immunotherapy through damaging mismatch repair, promoting tumor mutation, up-regulating the expression of PD-L1 protein, and regulating the immune microenvironment." (PMID 34805154, 2021). "Moreover, in vivo ARID1A-deficient ovarian cancer models exhibit an increased number of tumor-infiltrating lymphocytes, a higher tumor mutation load, and elevated PD-L1 levels." (PMID 33641055, 2021). "Similarly, in germ cell tumors, ARID1A deficiency produced by CRISPR/Cas9 gene editing or pharmacological inhibition considerably sensitized tumor cells towards ATR inhibition." (PMID 34737943, 2021). "It elucidated that loss of ARID1A expression could upregulate the expression of Bcl-2 and contribute to the inhibition of apoptosis of tumor cells." (PMID 34715776, 2021). "In this study, our results showed that ARID1A mutation was linked to significant change of tumor morphology (denser cells and less stroma), suggesting that image features could be potential predictive biomarkers of immunotherapy response." (PMID 33869007, 2021). "Indeed, tumors arising in Mlh1−/− mice harbor multiple ARID1A missense mutations, resulting in loss-of-function of this tumor suppressor." (PMID 34206051, 2021). "Mir-185 has been implicated in regulating tumor-associated genes in various cancer types, but its function in ARID1A suppression is unknown." (PMID 34414106, 2021). "Through the review of the published studies, we discovered the role of ARID1A alterations or expression loss in the regulation of Bcl-2 expression and apoptosis of tumor cells which might participate into the resistance to EGFR-TKIs." (PMID 34715776, 2021). "We also found that TAMs and cytotoxic T cells were also excluded from the vicinity of tumour cells in ARID1A mutated OCCCs, suggesting that the exclusion of these immune effectors could determine the host response in ARID1A mutant OCCCs." (PMID 34359755, 2021). "It indicates that ARID1A loss plays a role in tumor progression." (PMID 34257552, 2021). "Mounting evidence suggests ARID1A variation is commonly associated with multiple cancers, including gynecologic cancers, urothelial carcinoma, and gastrointestinal cancer, with a mutational rate from 3.6 to 45.2% depending on different tumor types." (PMID 34249744, 2021). "Three such strategies have been proposed to date: prioritizing a gemcitabine-based chemotherapeutic regimen, synthetic lethal therapy targeting vulnerabilities conferred by SWI/SNF deficiency, and immune checkpoint blockade therapy that exploits the high mutational burden of ARID1A-deficient tumor." (PMID 33917230, 2021). "The predictive value of ARID1A mutation on immunotherapy was also confirmed in other tumor types." (PMID 35003124, 2021). "Our data also indicated that deleterious mutations in ARID1A promote tumor invasion and metastasis." (PMID 32483112, 2020).